SCG3 (secretogranin III)
Description:
Member of the granin protein family that regulates the biogenesis of secretory granules. Acts as a sorting receptor for intragranular proteins including chromogranin A/CHGA (By similarity). May also play a role in angiogenesis. Promotes endothelial proliferation, migration and tube formation through MEK/ERK signaling pathway.
Synonyms: SgIII; FLJ90833
Tractability: Antibody: UniProt places it where antibodies can reach, with high confidence; its Gene Ontology location is reachable by antibodies, with high confidence; UniProt predicts a signal peptide or a membrane-spanning region. PROTAC: ubiquitination databases record sites on it; its protein half-life has been measured.
Gene: Protein-coding gene on chromosome 15 (51,681,492 to 51,721,026, forward strand). Ensembl gene ENSG00000104112.
Subcellular location: Cytoplasmic vesicle, secretory vesicle; Cytoplasmic vesicle, secretory vesicle membrane; Secreted
Subcellular location (Human Protein Atlas): Vesicles; Predicted to be secreted
Pathways (Reactome):
Metabolism of proteins: Post-translational protein phosphorylation; Regulation of Insulin-like Growth Factor (IGF) transport and uptake by Insulin-like Growth Factor Binding Proteins (IGFBPs)
Hemostasis: Platelet degranulation
Gene Ontology:
Molecular function: protein binding; RNA binding
Biological process: protein localization to secretory granule
Cellular component: extracellular region; endoplasmic reticulum lumen; secretory granule lumen; secretory granule membrane; transport vesicle; transport vesicle membrane
Genetic constraint (gnomAD): Loss-of-function variants: 20 observed, 34.42 expected, observed/expected ratio (o/e) 0.58, 90% interval 0.41 to 0.84. The upper end of that interval is the gene's LOEUF score, 0.84, which puts it in group 3 of 6, group 1 being the genes least tolerant of losing a copy. Missense variants: 381 observed, 409.03 expected, observed/expected ratio (o/e) 0.93, 90% interval 0.86 to 1.01. Synonymous variants: 136 observed, 148.6 expected, observed/expected ratio (o/e) 0.92, 90% interval 0.8 to 1.05.
Homologues: Orthologues: chimpanzee SCG3 (99% identical), dog SCG3 (93% identical), rabbit SCG3 (92% identical), pig SCG3 (91% identical), macaque SCG3 (91% identical), mouse Scg3 (89% identical), rat Scg3 (88% identical), guinea pig SCG3 (85% identical), tropical clawed frog scg3 (59% identical), zebrafish scg3 (53% identical).